CCAT2 (colon cancer associated transcript 2)
Diseases named in the same sentence as CCAT2 in open-access papers (continued):
Sharing a sentence is not in itself a finding about the gene and the disease.
osteosarcoma (5 papers, 2018 to 2022). A usually aggressive malignant bone-forming mesenchymal neoplasm, predominantly affecting adolescents and young adults. "It has been revealed that in osteosarcoma, CCAT2 serves as an oncogene to regulate miR-200b/VEGF axis to enhance cell progression and cell mobility." (PMID 34386421, 2021). "LncRNA CCAT2, a marker of poor prognosis in patients with osteosarcoma, was found to promote EMT in osteosarcoma cells." (PMID 32960485, 2021). "The expression of CCAT2 was up‐regulated in 26 osteosarcoma cases (26/40, 65%) compared with the normal adjacent tissues." (PMID 29502343, 2018). "Ectopic expression of CCAT2 promoted osteosarcoma cell invasion and increased the expression of mesenchymal markers N‐cadherin, vimentin and snail mRNA and decreased the expression of N‐cadherin marker E‐cadherin." (PMID 29502343, 2018). "In our study, we indicated that CCAT2 expression was up‐regulated in osteosarcoma tissues and cell lines (SOSP‐9607, MG‐63, U2OS and SAOS‐2)." (PMID 29502343, 2018). "Osteosarcoma cases with the higher CCAT2 expression had a poorer disease‐free survival and shorter overall survival time compared to those with the lower expression." (PMID 29502343, 2018). "Overexpression of CCAT2 promoted the osteosarcoma cell proliferation and invasion, indicating that CCAT2 acted an oncogenic role in osteosarcoma." (PMID 29502343, 2018). "In this study, we aimed to investigate CCAT2 expression level in osteosarcoma tissues and cell lines." (PMID 29502343, 2018). "CCAT2 expression was up‐regulated in osteosarcoma cell lines (SOSP‐9607, MG‐63, U2OS and SAOS‐2) compared to the normal osteoblast cell line (hFOB)." (PMID 29502343, 2018). "In general, CCAT2 expression level was higher in osteosarcoma tissues than in the normal control tissues." (PMID 29502343, 2018). "In summary, the data from our study showed that CCAT2 expression was up‐regulated in osteosarcoma tissues and cell lines." (PMID 29502343, 2018). "CCAT2 was an independent prognostic factor for disease‐free survival and the overall survival time for osteosarcoma cases." (PMID 29502343, 2018). "Ectopic expression of CCAT2 promoted osteosarcoma cell proliferation, cell cycle and invasion and EMT progression." (PMID 29502343, 2018). "In this study, we indicated that CCAT2 expression was up‐regulated in osteosarcoma tissues and cell lines (U2OS, MG‐63, SOSP‐9607 and SAOS‐2)." (PMID 29502343, 2018). "We found that CCAT2 expression was up‐regulated in 26 osteosarcoma cases (26/40, 65%) compared with the adjacent tissues." (PMID 29502343, 2018). "We demonstrated that CCAT2 expression was elevated in osteosarcoma tissues and cell lines." (PMID 29502343, 2018). "To study whether CCAT2 was involved in the osteosarcoma metastasis, we measured the effects of CCAT2 on the invasion of the osteosarcoma cells." (PMID 29502343, 2018). "We also examined the role of CCAT2 in osteosarcoma cell migration, proliferation and cycle." (PMID 29502343, 2018). "In addition, osteosarcoma cases with higher CCAT2 expression had a poorer disease‐free survival and shorter the overall survival time compared to those with lower expression." (PMID 29502343, 2018). "Next, we investigated the functional role of CCAT2 in osteosarcoma cell." (PMID 29502343, 2018). "We firstly detected CCAT2 expression in osteosarcoma tissues." (PMID 29502343, 2018). "In this study, we firstly analysed the expression of CCAT2 in osteosarcoma tissues." (PMID 29502343, 2018). "Furthermore, the expression of CCAT2 was up‐regulated in osteosarcoma cell lines (MG‐63, SOSP‐9607, U2OS and SAOS‐2) compared to the hFOB." (PMID 29502343, 2018). "Overexpression of CCAT2 promoted osteosarcoma cell proliferation, invasion and cell cycle." (PMID 29502343, 2018). "In addition, osteosarcoma cases with higher CCAT2 expression had a poorer disease‐free survival and shorter overall survival time compared to those with lower CCAT2 expression." (PMID 29502343, 2018).
osteosarcoma (continued). "Interestingly, CCAT2 was reported to target miR-200b to regulate osteosarcoma cell progression." (PMID 34386421, 2021). "However, the role of CCAT2 in the development of osteosarcoma remains unknown." (PMID 29502343, 2018). "CCAT2 overexpression promoted the LATS2 and c‐Myc expression in osteosarcoma cell." (PMID 29502343, 2018). "However, the functional role and expression pattern of CCAT2 in osteosarcoma have not been elucidated." (PMID 29502343, 2018). "However, the role of CCAT2 in the development of osteosarcoma has not been elucidated." (PMID 29502343, 2018).
cervical squamous cell carcinoma (4 papers, 2017 to 2022). A squamous cell carcinoma arising from the cervical epithelium. "Additionally, the overexpression of CCAT2 correlates with poor prognosis in squamous cell carcinoma of the cervix." (PMID 34499007, 2021).
lung adenocarcinoma (4 papers, 2016 to 2020). A carcinoma that arises from the lung and is characterized by the presence of malignant glandular epithelial cells. "Significant overexpression of lncRNAs-CCAT2 was found in lung adenocarcinoma." (PMID 30071841, 2018). "CCAT2 upregulation was reported in lung adenocarcinoma but not in squamous cell carcinoma." (PMID 32117734, 2020).
pituitary adenomas (4 papers, 2019 to 2025). "CCAT2 was upregulated in pituitary adenomas in comparison with adjacent normal tissue and associated with an aggressive tumor phenotype." (PMID 34830370, 2021). "CCAT2 overexpression in human pituitary adenoma cells occurs partly due to the transcription factor E2F1 binding to its promoter region and promoting transcription." (PMID 40362297, 2025). "The E2F1-induced activation of CCAT2 enhances the interaction of CCAT2 with PTTG1 to promote the progression of pituitary adenomas." (PMID 34499007, 2021). "Increased CCAT2 levels were shown to inhibit degradation of the Securin protein, which could explain the aggressive phenotype of the pituitary adenomas." (PMID 34830370, 2021). "Therefore, CCAT2 exerts an oncogenic function in pituitary adenomas." (PMID 40362297, 2025).
thyroid cancer (4 papers, 2020 to 2024). "This study aimed to evaluate the association of rs6983267 in CCAT2 gene with thyroid cancer susceptibility in the Azeri population of Iran." (PMID 37525664, 2023). "More recent studies have identified associations between the rs6983267 (POU5F1B, POU class 5 homeobox 1B and/or CCAT2, colon cancer associated transcript 2; 8q24) and thyroid cancer in different populations." (PMID 33551988, 2020).
triple-negative breast carcinoma (3 papers, 2021 to 2022). An invasive breast carcinoma which is negative for expression of estrogen receptor (ER), progesterone receptor (PR), and human epidermal growth factor receptor 2 (HER2). "For example, lncRNA colon cancer associated transcript 2 (CCAT2), which is located on 8q24.21, was reported to upregulate OCT4 expression by transactivated hPOU5F1P1 in human triple negative breast cancer." (PMID 35907897, 2022). "Consistent with that finding, CCAT2 expression was overexpressed in triple-negative breast cancer, and its oncogenic function was validated both in vitro and in vivo." (PMID 34386421, 2021).
cervical intraepithelial neoplasia (2 papers, 2022 to 2023). "The relative expression level of CCAT2 in primary CC patients was significantly higher than that in cervical intraepithelial neoplasias (CIN) patients and healthy controls (both P < 0.001)." (PMID 35115025, 2022).
metastatic colorectal cancer (2 papers, 2015 to 2023). "LncRNA, colon cancer associated transcript 2 (CCAT2), was found to have increased expression in metastatic colorectal cancer patient tumor samples." (PMID 26253106, 2015). "Knockdown of CCAT1, CCAT2, and MYC resulted in increased migratory and invasive potential in metastatic colorectal cancer cell lines." (PMID 37347737, 2023). "Gene expression, cancer cell migration, invasion, and proliferation were studied after siRNA-mediated knockdown of CCAT1, CCAT2, and MYC in metastatic colorectal cancer cell lines Colo205 and HROC277Met2." (PMID 37347737, 2023). "Moreover, we were able to demonstrate the direct impact of CCAT1, CCAT2, and MYC on metastatic colorectal cancer cell migration by affecting targets of Wnt signaling, including the upregulation of PPARD." (PMID 37347737, 2023). "The altered progression of metastatic colorectal cancer might be mediated via the effects of CCAT1 and CCAT2 on Wnt signaling." (PMID 37347737, 2023).
benign breast disease (1 paper, 2022). "In patients with benign breast disease, BCO40587 expression was positively correlated with BDNF (r = 0.67, P = 0.0003), HOTAIR (r = 0.6, P = 0.0019), CCAT2 (r = 0.52, P = 0.009), and PVT1 (r = 0.42, P = 0.44) expressions." (PMID 36376369, 2022).
brain tumor (1 paper, 2018). "An increased expression of CCAT2 and CCND2-AS1 induces proliferation, cell cycle progression and migration via the Wnt/β-catenin signaling pathway and downregulation of CCAT2 expression significantly reduces brain tumor growth in vivo." (PMID 30583549, 2018).
cervical tumor (1 paper, 2022). "Similarly, lncRNA CCAT2 prominently contributes to CC and it was reported that the knocking down of CCAT2 impeded cervical tumor cell proliferation and caused CC cells to enter the G1 phase of their cycle and stimulated them to undergo autophagy." (PMID 35886037, 2022).
chronic inflammatory demyelinating polyneuropathy (1 paper, 2021). "We investigated the expression levels of ANRIL, PICART1, MALAT1, CCAT1, CCAT2, and CCHE1 lncRNAs in acute and chronic inflammatory demyelinating polyneuropathy (AIDP and CIDP)." (PMID 33708228, 2021).
endometrial cancer (1 paper, 2022). Primary or metastatic malignant neoplasm involving the endometrium (mucous membrane that lines the endometrial cavity). "In line with our study, silencing CCAT2 suppressed endometrial cancer cell growth by inactivation of the mTOR pathway." (PMID 35170195, 2022). "Previous evidence showed that CCAT2 knockout repressed endometrial cancer cell growth and invasion by binding to miR‐216b, and miR‐216b could negatively regulate Bcl‐2 that could active the mTOR pathway." (PMID 35170195, 2022).
liver cancer (1 paper, 2019). An epithelial or non-epithelial malignant neoplasm that arises from the liver. "For patients with liver cancer, CCAT2 has been reported as an oncogene, and upregulation of CCAT2 was detected and associated with poor outcome." (PMID 31398859, 2019).
liver fibrosis (1 paper, 2022). "miR-34a-5p inhibitor undo protective regulation of sh-CCAT2 in liver fibrosis." (PMID 36482069, 2022). "Moreover, decreased CCAT2 diminished liver fibrosis through preventing phosphorylated Smad2/3, Smad4 and TGF-β1 signaling." (PMID 36482069, 2022). "Furthermore, clinical investigation showed that CCAT2 and Smad4 expression level were significantly induced, while miR-34a-5p was significantly decreased in HBV related liver fibrosis serum." (PMID 36482069, 2022). "However, no directly evidence support that miR-34a-5p and CCAT2 level in liver tissue are correlated with the progress of liver fibrosis." (PMID 36482069, 2022). "However, the contribution of CCAT2 and TGF-β1 signaling pathway in liver fibrosis and its intrinsic mechanism are not yet investigated." (PMID 36482069, 2022).
metastatic tumors (1 paper, 2014). "The role of CCAT2 in invasion and metastasis was further substantiated using a combination in vitro assays and CRC mouse xenograft models showing that CCAT2 overexpression resulted in a higher incidence and greater number of metastatic tumors." (PMID 25101115, 2014).
multiple myeloma (1 paper, 2021). "Moreover, when CCAT2 expression level was associated with classical multiple myeloma biomarkers such as IgA, β2MG, and HGB, the area under the curve (AUC) was significantly improved up to 0.974 (95% CI 0.958~0.990; p < 0.001)." (PMID 34830370, 2021). "In multiple myeloma, CCAT2 was upregulated in both peripheral blood and bone marrow when comparing patients with healthy controls." (PMID 34830370, 2021). "In addition, integrating the CCAT2 expression with classical biomarkers improved the sensitivity and specificity of multiple myeloma diagnoses." (PMID 34830370, 2021).
neuroblastoma (1 paper, 2024). Neuroblastoma (NB) is the most common solid, extracranial childhood tumor. "In neuroblastoma, CCAT2 upregulation is associated with decreased apoptosis and increased cell viability, proliferation, migration, and invasion." (PMID 38891878, 2024). "Aberrant CCAT2 expression has been associated with aberrant MYCN expression in neuroblastoma." (PMID 38891878, 2024).
non-alcoholic steatohepatitis (1 paper, 2019). "First, there are high levels of heterogeneity in HCC-related clinical indices, such as alcoholic and non-alcoholic steatohepatitis within the case group, presumably leading to distinct results concerning the association between CCAT2 and CASC8 gene variations and hepatic tumorigenesis." (PMID 31398859, 2019).
thyroid tumor (1 paper, 2023). A benign or malignant neoplasm affecting the thyroid gland. "Nevertheless, it was found that there is a correlation between the frequency of the G allele of rs6983267 SNP of the CCAT2 gene and the presence of thyroid tumors larger than 2 cm (x2=3.862, df=1, P=0.049)." (PMID 37525664, 2023). "CCAT2 (Colon Cancer Associated Transcript 2) is a lncRNA molecule involved in the occurrence and progression of thyroid tumors." (PMID 37525664, 2023).
cancer (107 papers, 2013 to 2026). A tumor composed of atypical neoplastic, often pleomorphic cells that invade other tissues. "For instance, lncRNA CCAT2 (colon cancer-associated transcript 2) promotes glycolysis and plays a pivotal role in increased glutamine metabolism in various cancers." (PMID 37161350, 2023). "Growing evidence indicates that lncRNA colon cancer-associated transcript 2 (CCAT2) is associated with cancers." (PMID 35115025, 2022). "The serum level of sEVs containing lncRNA-CCAT2 (colon cancer associated transcript 2) was increased in cancer tissue and serum from CRC patients." (PMID 35163305, 2022). "Various studies analyzed the association between CCAT2 expression level in cancer, identifying a direct association between CCAT2 upregulation and disease progression, invasion, positive lymph nodes, and metastasis." (PMID 34830370, 2021). "Similar to other cancers, upregulation of CCAT2 enhances the EMT and is associated with a poor prognosis." (PMID 34830370, 2021). "The colon cancer associated transcript 2 (CCAT2) lncRNA is encoded by a gene located on human chromosome 8." (PMID 34499007, 2021). "CCAT2 harbours the SNP rs6983267, which was reported to be associated with risk of many kinds of cancers." (PMID 34409736, 2021). "Colon cancer-associated transcript 2 (CCAT2) is an intensively studied lncRNA with important regulatory roles in cancer." (PMID 34830370, 2021). "Overexpression of CCAT2 has been linked to various types of cancer, including CRC, breast, lung, esophageal squamous cell carcinoma, and gastric cancers." (PMID 34868956, 2021). "Colon cancer‐associated transcript 2 (CCAT2), located in the hotspot of the tumor‐related rs6983267 SNP, has been associated with increased predisposition for several cancers." (PMID 32249459, 2020). "Similar to ANRIL, the CCAT2 lncRNA gene, located in chromosomal region 8q24.21, has been implicated in several malignancies, and CCAT2 expression is increased in many types of cancer." (PMID 33329688, 2020). "High CCAT2 expression is associated with the overall survival, progression-free survival lymph node and distant metastases of human cancers." (PMID 33371204, 2020). "The level of CCAT2 expression in tumor tissues is higher than that in paired normal tissues and is significantly associated with a poor prognosis in cancer patients." (PMID 32908615, 2020). "In summary, CCAT2 can be a potential biomarker associated with the progression and prognosis of human cancer." (PMID 32908615, 2020). "LncRNA colon cancer associated transcript 2 (CCAT2) is a promoter of cell proliferation and its upregulation is observed in several cancers." (PMID 32498309, 2020). "Our study analyzed a large number of publication data and TCGA databases to identify the association of CCAT2 expression with clinicopathological factors and to explore the regulatory mechanisms in human cancers." (PMID 32908615, 2020). "Colon cancer-associated transcript 2 (CCAT2) is located at the 8q24 region, and its genomic locus encompasses the SNP rs6983267 which is closely associated with increased risks for many cancers." (PMID 31275444, 2019). "Mechanistically, CCAT2 can alter cancer metabolism depending on the allele transcribed through altered binding affinity to pre-mRNA cleavage (CFIm) splicing factors." (PMID 29113413, 2017). "The rationale for analyzing CCAT2 and miR-145 cooperation is because CCAT2 promotes tumor growth and metastasis, causing a reduced sensitivity to chemotherapy which is the property related to cancer stem cells (CSCs)." (PMID 28964256, 2017). "The CCAT2 genomic locus contains certain polymorphisms that have been demonstrated to be associated with susceptibility to various cancers, as well as with the risk of metastasis in inflammatory breast cancer." (PMID 28480695, 2017). "Some meta-analyses focused on the association of lncRNAs such as BANCR, HOTTIP, CCAT2, and metastasis as well as prognosis of cancers; all of them were based on the lncRNAs detected in tissues." (PMID 29088881, 2017).